UPF1 (UPF1 RNA helicase and ATPase)
Diseases named in the same sentence as UPF1 in open-access papers (continued):
Sharing a sentence is not in itself a finding about the gene and the disease.
pancreatic adenosquamous carcinoma (10 papers, 2016 to 2022). A carcinoma that arises from the pancreas showing both ductal and squamous differentiation. "Mutations in the UPF1 gene detected in pancreatic adenosquamous carcinoma (ASC) tumors are the first known example of the NMD gene undergoing genetic alteration in human tumors." (PMID 35442152, 2022). "Liu and colleagues found that UPF1 gene is commonly mutated in Pancreatic adenosquamous carcinoma." (PMID 34922601, 2021). "For example, NMD effector upf1 is frequently mutated in pancreatic adenosquamous carcinoma." (PMID 28874147, 2017). "UPF1 was found down-regulated in pancreatic adenosquamous carcinoma, here, in our study, we found UPF1 was also down-regulated in HCC." (PMID 26759305, 2016). "The first report about the relationship between UPF1 and human tumor is pancreatic adenosquamous carcinoma." (PMID 26759305, 2016). "Liu and his colleagues found that UPF1 was down-regulated in pancreatic adenosquamous carcinoma (ASC) and the UPF1 gene is commonly mutated in pancreatic adenosquamous carcinoma." (PMID 26759305, 2016). "More intriguing is the fact that a mutation in UPF1 (NMD factor) has been reported as a driver mutation in two different types of cancers: Inflammatory Myofibroblastic Tumors (benign tumor) and in Pancreatic Adenosquamous Carcinoma." (PMID 36443756, 2022). "On the other hand, we should not disregard that the reported UPF1 mutation in Pancreatic Adenosquamous Carcinoma might not lead to loss of NMD activity as shown by a recent study." (PMID 36443756, 2022). "This suggests that UPF1 does not seem to be involved in pancreatic adenosquamous carcinoma." (PMID 33404013, 2021).
colorectal cancer (9 papers, 2008 to 2024). A primary or metastatic malignant neoplasm that affects the colon or rectum. "Genes implicated in the NMD pathway, such as Upf1, Upf2, Smg1, Smg6, and Smg7, are expressed in higher levels in colorectal cancer (CRCs) with microsatellite stability, and promote tumor growth in xenograft models." (PMID 37888706, 2023). "The downregulation of the NMD factor UPF1 was shown to decrease proliferation in endometrial cancer and colorectal cancer cells." (PMID 37349371, 2023). "UPF1 also participated in tumorigenesis and cancer progression of colorectal cancer (CRC) by UPF1-mediated mRNA destabilization regulating NR4A1." (PMID 35871061, 2022). "However, the role of UPF1 in oxaliplatin resistance in colorectal cancer (CRC) remains unknown." (PMID 34021129, 2021). "After silencing NR4A1AS in colorectal cancer cells, the NR4A1 mRNA bound to UPF1 was seen to almost double." (PMID 33732285, 2021). "To further test the UPF1 and EJC dependence of proximal 3′UI-containing NMD targets in human cells, we knocked down UPF1 or EIF4A3 in a human colorectal carcinoma cell line (HCT116), and assessed levels of a subset of 3′UI-containing transcripts." (PMID 32502192, 2020). "In contrast, transient silencing of UPF1 and/or UPF2 in MSI and MSS colorectal cancer cells (HCT116, LoVo, Co115, LS174T, SW480, COLO320) did not lead to significant alterations of cell growth and/or death in our hands (data not shown)." (PMID 18612427, 2008).
glioma (8 papers, 2019 to 2022). A benign or malignant brain and spinal cord tumor that arises from glial cells (astrocytes, oligodendrocytes, ependymal cells). "In glioma, UPF1 was reported to be downregulated in U87 and LN229 cell lines after acting with LncRNA PVT1." (PMID 35871061, 2022). "UPF1 bound to Linc-00313 in glioma and enhanced its stability to promote proliferation, invasion, and migration." (PMID 35318304, 2022). "As a key factor of SMD, UPF1 interacts with a variety of lncRNAs, and plays an important role in tumorigenesis and the progression of glioma." (PMID 33732285, 2021). "Knocking down the expression of Linc00313 or UPF1 can inhibit the proliferation, invasion and migration of glioma cells, and promote apoptosis." (PMID 33732285, 2021). "LncRNA CYTOR was up-regulated in glioma cells and tissues, and CYTOR overexpression partially reversed the inhibition of UPF1 on the proliferation and migration of glioma." (PMID 33318318, 2020). "The expression of UPF1 in glioma tissues and U87, U251 cells was significantly higher than that in normal brain tissues and HA cells." (PMID 31427569, 2019). "This study first showed that UPF1 and Linc-00313 were highly expressed in glioma tissues and U87 and U251 cell lines." (PMID 31427569, 2019). "LINC00152 is upregulated in glioma tissue and cells and negatively correlates with UPF1 levels." (PMID 36033524, 2022). "So in gliomas, UPF1 could not only act with LncRNA PVT1 to aggravate the progression of glioma but can bind circRPPH1 to help strengthen the malignant phenotype." (PMID 35871061, 2022). "UPF1 and Linc00313 are both upregulated in glioma tissues and cells." (PMID 33732285, 2021). "UPF1 appears to delay the degradation of Linc00313 and enhance the effect of Linc00313 on glioma." (PMID 33732285, 2021). "At present, the expression and functions of UPF1 and Linc-00313 in glioma remains uncharted." (PMID 31427569, 2019). "Knockdown of UPF1 or Linc-00313 significantly inhibited malignant biological behaviors of glioma cells by regulating miR-342-3p and miR-485-5p, which are downregulated and functioned as tumor suppressors in glioma." (PMID 31427569, 2019). "UPF1 and Linc-00313 were both upregulated in glioma tissues and cells." (PMID 31427569, 2019). "At the same time, Zic4 could positively regulate the transcriptional expression of UPF1 and Linc-00313, thus formed a positive-feedback loop that regulated the biological behaviors of glioma cells." (PMID 31427569, 2019). "In this study, the endogenous expression of UPF1, Linc-00313, miR-342-3p, miR-485-5p, Zic4, and SHCBP1 in glioma tissues and cells were determined." (PMID 31427569, 2019). "Such as, UPF1 regulates the progression of glioblastoma cells by improving the stability of linc‐00313,33 SRSF1 stabilized lncRNA NEAT1 to regulate the cell cycle progression in glioma." (PMID 33128346, 2020). "The study is the first to prove that the UPF1-Linc-00313-miR-342-3p/miR-485-5p-Zic4-SHCBP1 pathway forms a positive-feedback loop and regulates the biological behaviors of U87 and U251 cells, which might provide a new therapeutic target for glioma." (PMID 31427569, 2019).
breast cancer (6 papers, 2018 to 2025). A primary or metastatic malignant neoplasm involving the breast. "Another example of a cancer-relevant lncRNA is PVT1, known to be involved in cancer, which is significantly upregulated in breast cancer cell lines and promotes breast cancer cell proliferation and metastasis, through binding to mir-128-3p and UPF1." (PMID 37624034, 2023). "In addition, PVT1 binds to the UPF1 protein, thereby inducing epithelial–mesenchymal transition, proliferation and metastasis in breast cancer cells." (PMID 34922601, 2021). "PVT1 may act as an oncogene in breast cancer through binding miR-128-3p and UPF1 and represents a potential target for BC therapeutic development." (PMID 34922601, 2021). "The plasmacytoma variant translocation 1 (PVT1) lncRNA upregulated in breast cancer (BC) has been proposed to act as an oncogene through binding miR-128-3p and UPF1 and promoting EMT and, thus, proliferation and metastasis." (PMID 36766761, 2023).
glioblastoma (6 papers, 2019 to 2022). The most malignant astrocytic tumor (WHO grade IV). "Linc‐00313, which is stabilized by UPF1, regulates miR‐342‐3p and miR‐485‐5p, eventually accelerating the progression of glioblastoma." (PMID 34890108, 2022). "In this study, we elucidated the function and possible effect and molecular mechanisms of lncRNA-Linc-00313 on the biological behaviors of glioblastoma cells as well as UPF1 function as a RNA-binding protein to enhance its stability." (PMID 31427569, 2019). "Furthermore, Oncomine database revealed that UPF1 was upregulated in glioblastoma tissues which corroborated the findings of this study." (PMID 31427569, 2019).
viral infection (6 papers, 2018 to 2024). "While we propose that UPF1 is one player in the widespread dysregulation of these interactions, further studies are needed to elucidate disruptions in nuclear translocation during viral infection." (PMID 36603024, 2023). "UPF1 plays an essential role in viral infection development." (PMID 36766761, 2023). "The significance of UPF1 in human viral infections is discussed in detail below." (PMID 36766761, 2023). "Additionally, UPF1 was found to be involved in the cellular response towards viral infection." (PMID 36766761, 2023). "The role of UPF1 in future work should also be investigated in terms of host gene dysregulation within NMD disorders and other RNA decay pathway processes following viral infection." (PMID 36766761, 2023). "NMD was first found to inhibit viral infection when increased infectivity of Sindbis virus (SINV)-like particles was observed in a transgenic Drosophila strain, where NMD was abrogated by co-expression of a dominant negative UPF1 mutant." (PMID 36979701, 2023). "Intriguingly and in contrast to HCV, PYM1, along with MAGOH and UPF1, was identified as an anti-viral factor of WNV, DENV and ZIKV (who are from a different Flaviviridae genus than HCV) because knockdown of PYM1 increased viral infection and/or RNA levels in HEKs cells." (PMID 36979701, 2023).
amyotrophic lateral sclerosis (5 papers, 2017 to 2023). Amyotrophic lateral sclerosis (ALS) is a neurodegenerative disease characterized by progressive muscular paralysis reflecting degeneration of motor neurons in the primary motor cortex, corticospinal tracts, brainstem and spinal cord. "Many of those targets are significantly increased by UPF1 knockdown (KD), and are mutated or misregulated in neuronal diseases, such as spastic paraparesis, amyotrophic lateral sclerosis (ALS), frontotemporal dementia (FTD) and autism spectrum disorder." (PMID 36766761, 2023). "Indeed, a protective role for UPF1 has already been shown in primary neuronal models of amyotrophic lateral sclerosis (ALS) and frontotemporal dementia (FTD) induced by overexpression of the RNA-binding proteins, TDP43 and FUS." (PMID 32616520, 2020). "Interestingly, increasing NMD activity, such as by overexpressing UPF1, can alleviate the phenotypes of amyotrophic lateral sclerosis (ALS) in both in vitro and in vivo models." (PMID 28533900, 2017).
endometrial cancer (5 papers, 2020 to 2023). Primary or metastatic malignant neoplasm involving the endometrium (mucous membrane that lines the endometrial cavity). "The PVT1/miR-136/Sox2/UPF1 axis provides a promising novel approach for the treatment of endometrial cancer, especially refractory endometrial cancer." (PMID 36869031, 2023). "In studies of endometrial cancer, UPF1 expression has been found to be elevated and promotes the stemness of ECSCs." (PMID 36869031, 2023). "The expression of UPF1 in endometrial cancer tissues was higher than that in normal endometrium and higher in ECSCs than in non-stem cells." (PMID 36869031, 2023). "We aimed to investigate the mechanism by which PVT1 regulates the expression of Sox2 and UPF1 by targeting miR-136, thereby affecting the malignant biological behavior and cell stemness of endometrial cancer cells (ECCs) and ECSCs." (PMID 36869031, 2023). "Sox2 can act as a transcription factor to positively regulate Up-frameshift protein 1 (UPF1) expression, thereby exerting a tumor-promoting effect on endometrial cancer." (PMID 36869031, 2023). "We demonstrate that the PVT1/miR-136/Sox2/UPF1 axis plays an important role in the progression and maintenance of endometrial cancer." (PMID 36869031, 2023). "The expression of UPF1 in endometrial cancer tissues is higher than that in adjacent tissues, which can promote the growth and progression of endometrial cancer, increase the activity of the mTOR pathway, inhibit autophagy, and promote the malignant behavior and stemness of ECSCs." (PMID 36869031, 2023). "This enhances UPF1 transcription and promotes the malignant biological behavior and TSC characteristics of endometrial cancer." (PMID 36869031, 2023). "Through ChIP and dual-luciferase reporter assays, we found that Sox2 acts as a transcription factor for UPF1, and the overexpression of Sox2 in endometrial cancer non-stem cells and ECSCs can increase the expression of UPF1." (PMID 36869031, 2023). "The relationship among UPF1, the mTOR pathway and autophagy has not been reported in endometrial cancer." (PMID 34520393, 2021).
HIV-1 infection (5 papers, 2012 to 2024). The type species of lentivirus and the etiologic agent of acquired immunodeficiency syndrome (AIDS). "Therefore we wanted to determine the potential association of some of the main NMD factors such as Upf1, Upf2, and Upf3 in Staufen1-containing RNPs in the absence or presence of HIV-1 infection." (PMID 23125841, 2012). "In the context of HIV-1 infection, UPF1 enhanced both vRNA stability and viral gene expression in an NMD- independent manner." (PMID 30732620, 2019). "To determine whether the expression of these proteins is modulated during HIV-1 infection, we assessed the levels of UPF1, UPF2 and SMG6 expression in HIV-1-infected primary MDMs using an HIV-1 reporter construct called NL4-3-Bal-IRES-HSA." (PMID 30732620, 2019). "UPF1-mediated viral RNA nuclear export depends on Exportin-1 (also known as CRM1), which is consistent with the observation that UPF1 co-immunoprecipitates with Rev, CRM1, DDX3, and Nup62 in the context of HIV-1 infection." (PMID 38400005, 2024). "In order to address this question, we conducted shRNA-mediated knockdown of UPF1 in primary CD4+ T cells and observed the effects on vRNA levels and pr55Gag expression upon HIV-1 infection by FISH-Flow." (PMID 29954456, 2018). "This might also be true for UPF1’s newly characterized role in HIV-1 reverse transcription of the vRNA early in HIV-1 infection, at which stage UPF2 still has no role." (PMID 26492277, 2015).
inflammatory myofibroblastic tumor (5 papers, 2017 to 2023). A multinodular intermediate fibroblastic neoplasm that arises from soft tissue or viscera, in children and young adults. "In inflammatory myofibroblastic tumors, it was demonstrated that somatic mutations in UPF1 triggered alternative splicing of UPF1 and disrupted the NMD pathway." (PMID 36833284, 2023). "Mutations in UPF1 have been identified in inflammatory myofibroblastic tumors (IMT)." (PMID 28533900, 2017). "For example, a recent work shows mutation in UPF1 in 13 out of 15 inflammatory myofibroblastic tumor (IMT) samples." (PMID 34852841, 2021). "A similar mechanism was also reported in inflammatory myofibroblastic tumors (IMT), where somatic mutations in UPF1 upregulated an NMD substrate mRNA encoding NF-κB, contributing to immune infiltration associated with IMT." (PMID 36833284, 2023).
ZIKV infection (5 papers, 2018 to 2023). "Collectively, these data uncover a new function of UPF1 in mRNA transport in NPCs, a function perturbed upon loss of UPF1 expression during ZIKV infection." (PMID 36603024, 2023). "As the NMD pathway is a ubiquitous cellular surveillance mechanism, it is likely that ZIKV capsid targets UPF1 for degradation in any cell type that is susceptible to ZIKV infection." (PMID 30401782, 2018). "We speculate that the widespread nuclear retention of host mRNAs caused by the disruption of UPF1 function could be part of a central mechanism explaining pleiotropic effects of ZIKV infection on diverse cellular pathways." (PMID 36603024, 2023). "Thus, the reduction in nuclear UPF1 we observe in ZIKV-infected NPCs could contribute to the microcephaly phenotype caused by ZIKV infection in the fetal brain." (PMID 30401782, 2018). "Thus, the co-opting of the nuclear proteasome by ZIKV capsid to degrade UPF1 could disrupt its normal proteasomal activity and further contribute to the cytopathic effects associated with ZIKV infection." (PMID 30401782, 2018). "ZIKV infection or UPF1 knockdown resulted in polyadenylated transcript accumulation in the nucleus, causing decreased protein levels of FREM2, a UPF1 target, and consequent perturbation of NPC differentiation." (PMID 36603024, 2023). "Our results newly link UPF1 to the regulation of mRNA transport in NPCs, a process perturbed during ZIKV infection." (PMID 36603024, 2023). "We found that during ZIKV infection, UPF1 interacts with fewer transcripts, and these transcripts are associated with neurodevelopment." (PMID 36603024, 2023). "Many transcripts lost UPF1 occupancy during ZIKV infection, especially in the 3’UTR, and this loss of UPF1 was associated with altered transcript localization and only a minor effect on transcript abundance." (PMID 36603024, 2023). "The study also found that the inhibition of NMD regulator up-frameshift protein 1 (UPF1) enhanced ZIKV infection." (PMID 33671824, 2021). "Downregulation of Upf1 prior to infection significantly increases RNA viral levels and consequently viral production, suggesting that Upf1 regulates early stages of ZIKV infection." (PMID 31681621, 2019). "Endogenous UPF1 interacted with the ZIKV capsid protein in coimmunoprecipitation experiments, and capsid expression posttranscriptionally downregulated UPF1 protein levels, a process that we confirmed occurs during ZIKV infection." (PMID 30401782, 2018). "A further decrease in UPF1 levels by RNAi significantly enhanced ZIKV infection in NPC cultures, consistent with a model in which NMD restricts ZIKV infection in the fetal brain." (PMID 30401782, 2018). "UPF1 transcript levels were not decreased in ZIKV-infected cells or following ZIKV capsid overexpression, indicating that UPF1 is posttranscriptionally downregulated during ZIKV infection (respectively)." (PMID 30401782, 2018). "To confirm that UPF1 protein levels are dysregulated during ZIKV infection, we performed Western blot analysis of infected Huh7 cells and NPCs." (PMID 30401782, 2018). "Instead, we found a significant increase in the number of infected cells in NPC cultures when UPF1 was depleted, indicating that UPF1 regulates permissivity of NPCs to ZIKV infection at an early stage prior to viral RNA replication." (PMID 30401782, 2018). "To test the effect of lowered UPF1 levels on ZIKV infection, we further decreased UPF1 expression prior to ZIKV infection by transfecting NPCs with either nontargeting siRNA or a pool of UPF1-specific siRNAs." (PMID 30401782, 2018). "Importantly, overexpression of UPF1 reversed nuclear mRNA accumulation during ZIKV infection, confirming the functional relevance of UPF1 in the observed viral phenotype." (PMID 36603024, 2023). "Here we show that ZIKV infection disrupts subcellular partitioning of host transcripts critical for neurodevelopment in NPCs and functionally link this process to the up-frameshift protein 1 (UPF1)." (PMID 36603024, 2023).